ENSG00000252777
Synonyms: LOC124904809
Gene: Small Cajal body-specific RNA gene on chromosome 1 (28,689,665 to 28,689,794, forward strand). Ensembl gene ENSG00000252777.
Gene Ontology:
Biological process: RNA processing
Cellular component: Cajal body; nucleolus